BNIP3 (BCL2 interacting protein 3)
Diseases named in the same sentence as BNIP3 in open-access papers (continued):
Sharing a sentence is not in itself a finding about the gene and the disease.
pancreatic cancer (42 papers, 2009 to 2025). "A recent study has shown that BNIP3 is not only associated with autophagy but also reduces MHC-I expression in pancreatic cancer cells to mediate tumor immune escape." (PMID 40438322, 2025). "Low levels of BNIP3 at a late stage of pancreatic cancer promote chemoresistance and are associated with poor prognosis." (PMID 36831455, 2023). "BNIP3 is a tumor suppressor, the expression of BNIP3 was significantly reduced in pancreatic cancer and is associated with tumor size, clinical stage and LNM." (PMID 36454866, 2022). "BNIP3 loss in pancreatic cancer has been associated with decreased apoptosis in tumor cells, metastatic phenotypes and poor prognosis, rendering BNIP3 a possible anti-tumor gene for this kind of malignancy." (PMID 30250843, 2018). "BNIP3 expression was significantly lower in pancreatic cancer tissues compared with normal epithelia and was associated with tumor size, clinical stage, and lymph node metastasis." (PMID 28968982, 2017). "Correlation analysis revealed that the expression of BNIP3 was negatively associated with Bcl-2 (r=-0.476, P=0.001) and positively associated with Bax in pancreatic cancer tissues (r=0.333, P=0.005)." (PMID 28968982, 2017). "The restoration of BNIP3 expression in pancreatic cancer cells in vitro, caused loss of ΔΨm, increase in ROS production, and apoptosis induction." (PMID 28968982, 2017). "Previous studies have indicated that hypermethylation of the BNIP3 promoter was found in pancreatic cancer, and the BNIP3L gene was infrequently mutated in a panel of primary breast and ovarian tumors." (PMID 26432836, 2015). "BNIP3 as a gene is strongly associated with intrinsic resistance to gemcitabine and frequently down regulated in pancreatic cancer." (PMID 22873289, 2012). "Loss of BNIP3 expression in pancreatic cancer is correlated with methylation of the BNIP3 promoter." (PMID 32850327, 2020). "In addition to the expression analysis of BNIP3 in pancreatic tumors, the results revealed that BNIP3 expression was associated with clinicopathological characteristics, including tumor size, clinical stage, and lymph node metastasis." (PMID 28968982, 2017). "A total of five out of the six pancreatic cancer cell lines indicated increased methylation levels in the promoter region of the BNIP3 gene that were associated with silencing of BNIP3 expression, whereas Patu8988 cells that exhibited low BNIP3 expression displayed partial methylation (26%)." (PMID 28968982, 2017). "Moreover, specific BNIP3 downregulation is associated with gemcitabine resistance of pancreatic cancer cells." (PMID 22291707, 2012). "In turn, epigenetic silencing of BNIP3 resulted in high aggressiveness of the pancreatic cancer cells." (PMID 40943612, 2025). "In pancreatic cancer cells, autophagy is linked to Integrin Subunit Beta 4 (ITGB4)‐ BCL2 interacting protein 3 (BNIP3) expression, with ITGB4/BNIP3 activation promoting MHC‐I engulfment by autophagosomes, aiding immune evasion." (PMID 40673641, 2025). "It was disclosed that upregulation of miR‐148b and‐152 led to the restoration of DNA methylation patterns to their normal states and facilitated TSGs re‐expression, such as SPARC and BNIP3 in pancreatic cancer cell lines (AsPC‐1 and MIA PaCa‐2)." (PMID 40387409, 2025). "BNIP3 promotes cell apoptosis in lung cancer and pancreatic cancer and is also a predictive factor for lung adenocarcinoma and small-cell lymphoma in individuals in the autophagy-related biomarker groups, indicating that BNIP3 is a prognostic marker." (PMID 38245717, 2024). "The elevated level of BNIP3 and decreased risk of death for patients with LUAD are concordant with the data for patients with pancreatic cancer." (PMID 37749074, 2023). "We can consider the BNIP3 as a potential target for new therapies aimed at treating pancreatic cancer." (PMID 37223030, 2023).
pancreatic cancer (continued). "Transfection of miR-148b or miR-152 in pancreatic cancer cells reactivated tumor suppressor genes such as BNIP3, SPARC, PENK, and TFPI-2 by downregulating DNMT1." (PMID 36959680, 2023). "BNIP3 was epigenetically silenced in pancreatic cancer, colorectal cancer, gastric cancer, leukemia and lymphoma." (PMID 32412667, 2020). "In fact, pancreatic cancer cells showed hypermethylation of the BNIP3 promoter that prevented HIF-1 binding and the subsequent activation of mitophagy that restrained mitochondrial mass and ROS production." (PMID 31210843, 2019). "BNIP3 appeared to be lost in invasive breast cancer and in almost 60% of pancreatic cancer patients where it correlated with poor survival." (PMID 31210843, 2019). "It is important to note that the binding of HIF1-α to the HRE BNIP3 promoter region is inhibited by methylation, thus affecting the expression of BNIP3 in pancreatic cancer cells." (PMID 28968982, 2017). "BNIP3 downregulation has been shown to enhance the resistance to 5-FU in pancreatic cancer cell lines suggesting that the expression of this protein is essential for the induction of tumor cell death." (PMID 28968982, 2017). "Univariate and multivariate analysis of survival indicated that the level of BNIP3 expression is an independent prognostic indicator in pancreatic cancer." (PMID 28968982, 2017). "Taken together the findings indicate that the reduced BNIP3 expression in pancreatic cancer results from epigenetic silencing at the BNIP3 promoter region due to methylation." (PMID 28968982, 2017). "The expression of BNIP3 was evaluated in a range of tumor specimens derived from patients with pancreatic cancer by immunohistochemical and immunofluorescence techniques." (PMID 28968982, 2017). "Previous studies have reported that BNIP3 expression can be induced under hypoxia in certain pancreatic cancer cell lines namely, PSN-1, T3M4, PANC-1, HPDE, CFPacl and SU86.86." (PMID 28968982, 2017). "In order to confirm the relationship between DNA methylation and BNIP3 silencing, we used MS-PCR to examine the methylation status of the six pancreatic cancer cell lines." (PMID 28968982, 2017). "The findings indicated that BNIP3 was significantly downregulated in pancreatic cancer resulting in reduced apoptosis induction." (PMID 28968982, 2017). "The mechanism of BNIP3-mediated apoptosis in pancreatic cancer was further investigated in in vitro cell lines under hypoxic and normoxic conditions." (PMID 28968982, 2017). "BNIP3 acted as a proapoptotic protein in pancreatic cancer cells and induced apoptosis via the mitochondrial pathway." (PMID 28968982, 2017). "Hypermethylation in the BNIP3 promoter occurs in a majority of tumors, including pancreatic cancer, hepatocellular carcinoma, colon cancer, and gastric cancer." (PMID 28968982, 2017). "Although BNIP3 expression is elevated in certain tumors namely, breast, lung and cervix in colorectal and pancreatic cancers BNIP3 is frequently epigenetically silenced, possibly reflecting the different functions of BNIP3 according to the different tissues." (PMID 28968982, 2017). "In the present study, the expression levels of BNIP3 in human pancreatic cancer tissues and the correlation with clinicopathological characteristics were investigated." (PMID 28968982, 2017). "BNIP3 protein was predominantly localized in the cytoplasm of cells in pancreatic cancer tissues, whereas a lesser amount of the protein was expressed in the nucleus." (PMID 28968982, 2017). "The survival time in 70 cases of pancreatic cancer following surgery was further compared with regard to BNIP3 expression." (PMID 28968982, 2017). "The results suggested that low BNIP3 expression correlated with the development of pancreatic cancer." (PMID 28968982, 2017). "The data suggest that BNIP3 reactivation is a potential target for therapeutic intervention against pancreatic cancer." (PMID 28968982, 2017).
pancreatic cancer (continued). "The expression of BNIP3 was undetectable in five of the six pancreatic cancer cells under normoxic conditions, whereas Patu8988 cells revealed low BNIP3 expression." (PMID 28968982, 2017). "The findings of the present study are in concordance with the study by Okami and colleagues, where it was found that BNIP3 was downregulated in pancreatic tumors (n=9) compared with normal tissues (n=8) by RT-PCR analysis." (PMID 28968982, 2017). "In the present study, the contribution of the proapoptotic protein BNIP3 in the induction of apoptosis in pancreatic cancer was examined." (PMID 28968982, 2017). "The expression of BNIP3 in pancreatic cancer cell lines was further explored in the presence of Aza-dC." (PMID 28968982, 2017). "The findings suggested that low BNIP3 expression is related to proliferative activity and reduced apoptosis in pancreatic cancer tissue." (PMID 28968982, 2017). "The expression of BNIP3 was restored by the methyltransferase inhibitor 5-aza-deoxycytidine (5-aza-dC), as was the hypoxia-mediated pancreatic cancer cell death." (PMID 28968982, 2017). "The data collectively suggested that BNIP3 reactivation is a novel therapeutic target for pancreatic cancer." (PMID 28968982, 2017). "The present study demonstrated that BNIP3 was significantly downregulated in pancreatic cancer and this correlated with a poor prognosis." (PMID 28968982, 2017). "BNIP3 was downregulated in pancreatic tumor tissues compared with the corresponding normal specimens, whereas the expression of this protein was absent in the pancreatic cancer cell lines investigated, with the exception of Patu8988 cells." (PMID 28968982, 2017). "The expression of BNIP3 in pancreatic cancer was demonstrated by Okami and colleagues under hypoxic conditions." (PMID 28968982, 2017). "The present study demonstrated that HIF-1α expression was significantly induced in pancreatic cancer cells cultured under hypoxic condition, whereas BNIP3 expression was undetectable." (PMID 28968982, 2017). "On the other hand, Bnip3 expression can be silenced in leukaemias and pancreatic, colorectal and gastric cancers, and lost Bnip3 or high AMBRA1 expression in pancreatic cancer correlate with worsened prognosis." (PMID 26611876, 2016). "Upon silencing BNIP3 in pancreatic cancer lines in vitro, the group observed a marked increase in chemoresistance to 5-FU and gemcitabine." (PMID 24782785, 2014). "A previous study has shown that pharmacological inhibition of G9a induces autophagy under hypoxia in pancreatic cancer cells via transcriptional upregulation of BNIP3, a pro-apoptotic member of the Bcl-2 family." (PMID 25027955, 2014). "As pancreatic cancer evolves, concomitant downregulation of BNIP3 makes it necessary that autophagy is induced by alternative pathways, as described hereunder." (PMID 22291707, 2012). "Nevertheless, microarray results indicated overexpression of BNIP3 in gemcitabine-sensitive pancreatic cancer cell lines." (PMID 22291707, 2012). "The epigenetic silencing of Bnip3 in some colorectal cancers and in pancreatic cancers, suggests that Bnip3 is deleterious to tumor development/progression." (PMID 22984526, 2012). "Decreased levels of BNIP3 mRNA and protein have been found in pancreatic cancer, colorectal and gastric cancer, and hematopoietic malignancies." (PMID 19505343, 2009). "This has been shown in pancreatic adenocarcinoma where the promoter of BNIP3 turned out to be methylated in all BNIP3-negative pancreatic cancer cell lines and in eight out of 10 pancreatic adenocarcinoma samples." (PMID 19505343, 2009). "Furthermore, the downregulation of BNIP3 expression in pancreatic cancer is responsible for chemoresistance and is connected with poor prognosis." (PMID 40943612, 2025). "Furthermore, miR‐148b and‐152, by regulating the expression of SPARC and BNIP3, play a crucial role in pancreatic cancer pathogenesis." (PMID 40387409, 2025).
pancreatic cancer (continued). "Studies have indicated that BNIP3 plays an important role in the regulation of autophagy, metabolic pathways, and metastasis-related processes in different tumor types and can be regulated by p21 to promote cell cycle arrest in pancreatic cancer." (PMID 38245717, 2024). "BNIP3 is downregulated and hypermethylated in pancreatic cancer in resistance against cell death." (PMID 36831455, 2023). "Patients with pancreatic cancer with low BNIP3 expression have a shortened OS." (PMID 37749074, 2023). "The same phenomenon was also seen in pancreatic cancer cells, which might be related to the cellular localization of BNIP3." (PMID 36200262, 2022). "Interestingly, in pancreatic cancer, BNIP3 downregulation contributes to chemotherapy resistance and is associated with poor patient prognosis, implying a tumor-suppressing role of BNIP3." (PMID 35201480, 2021). "The epigenetic silencing of BNIP3 could enhance the aggressiveness and metastasis of pancreatic cancer cells, and contribute to resistance to hypoxia-induced cell death in pancreatic cancer." (PMID 32587855, 2020). "In turn, restoration of BNIP3 expression provided pancreatic cancer cell death." (PMID 33207677, 2020). "In most cases, 5-Aza was used to restore normal BNIP3 expression, sensitizing pancreatic cancer cells via hypoxia-mediated apoptosis promotion and busulfan-resistant myeloid leukemia cells by upregulation of proapoptotic proteins, including BNIP3." (PMID 31835431, 2019). "The data indicate that BNIP3 expression is a new prognostic factor in pancreatic cancer." (PMID 28968982, 2017). "The absence of BNIP3 expression in pancreatic cancer cells was related to gene methylation that suppressed binding of HIF-1α to the BNIP3 promoter, whereas 5-Aza-2′-deoxycytidine (Aza-dC) treatment restored BNIP3 expression and sensitized pancreatic cancer cells to BNIP3-induced apoptosis." (PMID 28968982, 2017). "It is important to note that the contribution of additional transcription factors may be involved in the transcriptional activation of BNIP3 by HIF-1α in pancreatic cancer cells, as earlier noted for other types of cancers." (PMID 28968982, 2017). "The opposite effect was observed in pancreatic cancer cells, following BNIP3 silencing by RNAi." (PMID 28968982, 2017). "The functional interference of SIM2s with the activity of HIF1α on BNIP3 may be involved in the hypoxic regulation of BNIP3 in pancreatic cancer cells, although further studies are required to confirm this hypothesis." (PMID 28968982, 2017). "In the present study, the expression of BNIP3 in pancreatic cancer tissues, the correlation with clinicopathological characteristics and prognosis and the regulation of this protein in pancreatic cancer cell lines with regard to the induction of apoptosis were investigated." (PMID 28968982, 2017). "Demethylation by Ada-dC could restore BNIP3 expression and sensitize pancreatic cancer cells to BNIP3-induced apoptosis." (PMID 28968982, 2017). "Furthermore, knockdown of the transcription factor S100A4 enhances apoptosis of pancreatic cancer cells in response to gemcitabine via the induction of BNIP3 expression." (PMID 28968982, 2017). "Taken collectively, the data suggest that HIF1-α mediates activation of BNIP3 under hypoxic conditions that results in the induction of the mitochondrial pathway of apoptosis in pancreatic cancer cells, via the modulation of the expression of the proteins Bax, AIF and Bcl-2." (PMID 28968982, 2017). "Consequently, patients with pancreatic cancer that exhibit higher expression of BNIP3 possess a higher overall survival rate." (PMID 28968982, 2017). "Epigenetic silencing of the BNIP3 promoter appears to be the most common mechanism explaining down-regulation of BNIP3 during malignant progression in lung, colorectal, hematologic, liver, and pancreatic cancers although genomic deletion and repression by specific microRNAs has also been reported." (PMID 24350057, 2013).
pancreatic cancer (continued). "Indeed, CpG islands were found from the 5' end to the intron 2 (−1162/+538) of BNIP3 gene and methylation in these sites correlated with low expression of BNIP3 in pancreatic tumors where most of the CpG analyzed were specifically methylated in tumoral tissue." (PMID 24709797, 2013). "Also suppression of BNIP3 by siRNA reduced gemcitabine induced cytotoxicity in pancreatic cancer cells in vitro." (PMID 22873289, 2012). "However, in colorectal and pancreatic cancers BNIP3 is frequently epigenetically silenced." (PMID 34759953, 2021). "In addition, BNIP3 has a tumor suppressor effect in pancreatic cancer, colorectal cancer, and gastric cancer, which is related to hypermethylation of the BNIP3 promoter." (PMID 33262988, 2020). "BNIP3 level could be regulated by oncogenes and subsequently influences the cell fate of different types of tumors, e.g., castration-resistant prostate cancer or pancreatic cancer." (PMID 33207677, 2020). "However, the function of BNIP3 and the mechanism of the association of HIF-1α with the BNIP3 promoter in pancreatic cancer cells have not yet been fully elucidated." (PMID 28968982, 2017). "Notably in pancreatic cancer, BNIP3 expression is downregulated and this may contribute to the increased resistance of this type of cancer to 5-FU." (PMID 28968982, 2017). "Furthermore, BNIP3 negative expression (P=0.024) was found to be significantly associated with poor survival in pancreatic cancer patients, irrespective of the clinical stage and lymph node metastasis." (PMID 28968982, 2017). "However, forced expression of BNIP3 in pancreatic tumoral cell lines leads to apoptosis." (PMID 24709797, 2013). "We selected the marker genes (ADM, ERO1A, ENO2, BNIP3, and UPP1) of CAF-C2 to detect their expression in human pancreatic CAF-stellate cell (CAF118), human pancreatic cell (HPC-Y5), and human pancreatic cancer cell line." (PMID 36544710, 2022). "The expression of BNIP3 and HIF-1α proteins was investigated under normoxic and hypoxic conditions in the six pancreatic cancer cell lines." (PMID 28968982, 2017). "It was suggested miR-148b and -152 that are modifying methylation status of tumor suppressor genes such as BNIP3 and SPARC can be applied in killing the pancreatic cancer cells and decreasing the tumorigenicity of these cells." (PMID 29262657, 2017). "In summary, miRs that specifically target DNMT1 and modulate the methylation patterns of TSGs like BNIP3 and SPARC can potentially be utilised as a therapeutic approach for inducing apoptosis in pancreatic cancer cells and reducing their tumorigenic properties." (PMID 40387409, 2025). "BNIP3 has been reported to be absence of expression in advanced pancreatic cancer, and the recovery of BNIP3 expression made pancreatic cancer cells tend to die." (PMID 36200262, 2022). "The different roles of BNIP3 and NIX in pancreatic cancer require further investigation." (PMID 35201480, 2021). "The previous studies conducted by our group indicated that BNIP3 expression was significantly lower in pancreatic cancer tissues than in non-tumor tissues." (PMID 28968982, 2017). "A total of 25 out 70 specimens from pancreatic cancer tissues (35.7%) exhibited positive BNIP3 expression, whereas 45 out of 70 non-tumor samples (64.2%) exhibited negative BNIP3 expression." (PMID 28968982, 2017). "It was proposed that the hypoxic environment promoted an aggressive phenotype of pancreatic cancer cells that were BNIP3 negative and remained resistant to future BNIP3 induction." (PMID 28968982, 2017). "The overall survival of the patients with pancreatic cancer and positive BNIP3 expression was higher compared with the patients that were negative for BNIP3 (P<0.001)." (PMID 28968982, 2017). "The restoration of BNIP3 expression by treatment of negative BNIP3-pancreatic cancer cell lines with the DNA-methyltransferase inhibitor 5-Aza-2′-deoxycytidine (Aza-dC), rendered the pancreatic cancer cells more sensitive to hypoxia induced cell death." (PMID 28968982, 2017).